ENG (endoglin)
Diseases named in the same sentence as ENG in open-access papers (continued):
Sharing a sentence is not in itself a finding about the gene and the disease.
prostate carcinoma (37 papers, 2011 to 2025). A carcinoma that arises from epithelial cells of the prostate gland. "Prostate cancer has been associated with ACVR1 through endoglin, a TGFβ superfamily auxiliary receptor identified as a marker of tumour angiogenesis and neovascularisation." (PMID 31683698, 2019). "RELN and ALDH1A1 are expressed in prostate cancer, ENG, SI, FCGBP and PTPRT are associated with colonic tumors." (PMID 21533145, 2011). "Among urological malignancies, higher blood levels of endoglin have been found to be associated with higher preoperative serum prostate‐specific antigen, adverse pathologic features, as well as biochemical progression in prostate cancer patients." (PMID 34587660, 2022). "Evidence has shown that ENG suppresses the migration and invasion of prostate cancer cells and acts as a tumor-suppressor in prostate cancer." (PMID 39552710, 2024). "ENG expression is correlated with tumor progression and microvascular density, such as colon cancer, lung cancer, and prostate cancer, and is a key protein for tumor proliferation and metastasis." (PMID 36296203, 2022). "Previous in vitro studies have shown that FOXA1 increases pro-angiogenic factors, including EGF, endothelin-1, and endoglin in prostate cancer cells and promotes endothelial cell proliferation, migration, and tube formation." (PMID 35627227, 2022). "This is in agreement with previous studies reporting preoperative plasma endoglin to improve the accuracy for the prediction of pelvic lymph node metastasis in patients treated with radical prostatectomy for clinically localized prostate cancer." (PMID 34587660, 2022). "Endoglin (ENG) is another CAF marker associated with adverse outcomes, and it has been shown to promote castration‐resistant prostate cancer." (PMID 33600062, 2021). "In fact, ENG suppresses prostate cancer cell migration and invasion via the ALK2/SMAD1 pathway, and it inhibits tumor growth and metastasis in vivo, suggesting that ENG is a negative regulator of prostate cancer." (PMID 33804796, 2021). "Next to its high presence on endothelial cells, expression of endoglin has also been shown on fibroblast-like stromal cells at the invasive fronts of colorectal and prostate cancer." (PMID 33946583, 2021). "ENG is also upregulated in prostate cancer cells upon radiation and it promotes resistance to treatment." (PMID 33804796, 2021). "Additional research showed that the combination of androgen deprivation therapy (ADT) and TRC105 reduced castration-resistant prostate cancer progression through interruption of the communication between endoglin-expressing CAFs and prostate cancer cells." (PMID 33375670, 2020). "Indeed, ENG expression in CAFs stimulates EC recruitment and proliferation of prostate cancer cells through a mechanism that involves secreted factors such as components of the insulin growth factor (IGF) signaling pathway." (PMID 33804796, 2021). "Similarly, treatment with TRC105 led to a significant decline in the number of Tregs in patients with metastatic urothelial carcinoma and castration-resistant prostate cancer, making Tregs a novel target for ENG targeted therapy." (PMID 33804796, 2021). "Similarly, for OS, higher levels of ENG and GEM were associated with a worse OS in patients with PCa, and ENG was downregulated by deslanoside, suggesting an oncogenic role of ENG in prostate cancer." (PMID 34830961, 2021). "This hypothesis adds information to the endoglin roles observed in prostate cancer, yet the mechanistic process regulating endoglin-ACVR1 functions should still be defined." (PMID 31683698, 2019). "Recombinant endoglin localised in F-actin-rich membrane protrusions along the leading edge of migrating endothelial cells, similar to the localization observed in human prostate cancer cells." (PMID 26786759, 2016).
prostate carcinoma (continued). "Recent evidence has implicated endoglin, a TGFβ type III receptor and co-receptor, in cancer cell invasion in prostate cancer cell lines via activin A signaling, though endoglin has primarily been shown to propagate the signal by forming a complex with TGFβ and its receptors." (PMID 25560921, 2014). "Furthermore, when we targeted endoglin on these CAFs in a mouse model for experimental liver metastasis, a reduction in the number of metastases was detected, in line with earlier results reported for prostate cancer." (PMID 32059544, 2020). "On the contrary, ACVR1 could also phosphorylate endoglin, promoting prostate cancer cell migration." (PMID 31683698, 2019). "Additionally, Endoglin, a transforming growth factor beta superfamily auxiliary receptor, was shown to inhibit prostate cancer motility via activation of the Alk2/Smad1 pathway, and BMP7 inhibition of epithelial-to-mesenchymal transition was lost when Alk2 were knocked down in a melanoma cell line." (PMID 22457812, 2012). "The result of phase I of TRC105, a chimeric anti-endoglin (CD105) mAb, in metastatic castration-resistant prostate cancer shows good anti-angiogenic activity and that it is well tolerated." (PMID 29276515, 2017). "Besides ENG expression in tumor vessels, some neoplasms also present high levels of ENG in tumor cells, including melanoma, renal cell carcinoma (RCC), leukemias, certain subtypes of sarcomas, and breast, ovarian, endometrial, and prostate cancer." (PMID 33804796, 2021). "However, it has been reported that endoglin also interacts with and activates ACVR1, inhibiting prostate cancer cell migration." (PMID 31683698, 2019). "Endoglin (CD105), a type III transforming growth factor-beta/bone morphogenic protein (TGF-β/BMP) co-receptor, recognized as a marker of proliferating endothelia, is upregulated in several cancers, including prostate cancer." (PMID 29717261, 2018). "ENG expression was also dually examined in a subset of cases probed for ASPN expression in stroma adjacent to benign prostate (n = 10) and in Gleason grade 3 (n = 6), Gleason grade 4 with noncribriform morphology (n = 7), and Gleason grade 4 with cribriform morphology (n = 6) prostate cancer." (PMID 33600062, 2021).
melanoma (33 papers, 1996 to 2026). A malignant, usually aggressive tumor composed of atypical, neoplastic melanocytes. "Instead, in line with the characterization of CD31-CD105- as inhibitory cells, low CD105/ENDOGLIN mRNA expression in melanoma patients was associated with increased survival." (PMID 40592236, 2025). "In a study silencing endoglin using the GET of a plasmid-encoding shRNA against endoglin under a tissue-specific promoter in the same melanoma tumor model B16F10, complete, long-term regression was found in 44% of tumors." (PMID 32204304, 2020). "•Overexpression of endoglin by melanoma cells influences melanin production which is associated with an aggressive melanoma phenotype." (PMID 30225321, 2018). "The underlying data demonstrates that the expression of endoglin in murine melanoma cells influences melanin production in the cells." (PMID 30225321, 2018). "In this study we demonstrate that the targeting of endoglin with GET of plasmid DNA encoding shRNA against endoglin (pU6-antiCD105) represents a new option for targeted therapy of melanoma." (PMID 26712792, 2015). "In our recent study, endoglin was silenced with plasmids encoding shRNA against endoglin in a B16F10-luc melanoma tumor model with the purpose of testing two different promoters driving shRNA expression." (PMID 26712792, 2015). "Endoglin overexpression is associated with highly proliferative tumor endothelium and also with some tumors, including melanoma." (PMID 26712792, 2015). "In contrast to in vitro experiments, the B16F10 melanoma variant responded better to the therapy with GET of pU6-antiCD105 plasmid due to a higher expression of endoglin, resulting also in a high percentage of tumor cures." (PMID 26712792, 2015). "In our study, we confirmed that endoglin is expressed in two melanoma variants, B16F1 and B16F10." (PMID 26712792, 2015). "The aim of our study was to explore the anti-tumor effectiveness of endoglin silencing by electrotransfer of plasmid DNA encoding short hairpin RNA against endoglin in two murine B16 melanoma variants with different metastatic potential on cells, spheroids and subcutaneous tumors in mice." (PMID 26712792, 2015). "Proteomic comparison of SEVs and LEVs purified from melanoma cells identified the TGF-β co-receptor endoglin as a cargo that is unique to the SEV fraction." (PMID 41532547, 2026). "A quantitative proteomic comparison of exosomes purified from control and endoglin-KD melanoma cells revealed that the filopodia regulatory transmembrane molecule thrombospondin type 1 domain containing 7A (THSD7A) is reduced in endoglin-KD exosomes." (PMID 41532547, 2026). "Some immunity-related proteins were detected in melanoma, like CD14 as a particular protein in stage II melanoma and upregulated Endoglin/CD105." (PMID 36338621, 2022). "The possibility of the involvement of endoglin in the regulation of the biological properties of melanoma cells has been confirmed." (PMID 36150976, 2022). "It is possible that endoglin participates in the angiogenesis observed in thin melanomas, especially in tumors with metastases, but this study did not provide definitive statistical evidence." (PMID 36150976, 2022). "In a similar study, the video-intensity of lipid-shelled microbubbles coupled via streptavidin-biotin binding chemistry to anti-mouse rat integrin αv, VEGFR2, endoglin, and a control IgG was evaluated in a B16-F10 melanoma mouse model." (PMID 33946583, 2021). "Accordingly, ENG downregulation hinders invasiveness and abrogates tumor growth in preclinical models of Ewing sarcoma and melanoma." (PMID 33804796, 2021). "Similar effects were demonstrated in the study of silencing endoglin using GET in the same B16F10 melanoma model, resulting in increased immune cell infiltration and 11% of cured tumors that were 100% resistant to secondary challenge." (PMID 32204304, 2020).
melanoma (continued). "In this study, we examined repolarization of TAMs from M2- to M1-like phenotype in B16-F10 murine melanoma exerted by a combination of endoglin-based DNA vaccine and IL-12 and the effect of this reversion on tumor blood vessels." (PMID 29320562, 2018). "In this study, we examined repolarization of TAMs from M2- to M1-like phenotype in B16-F10 murine melanoma, exerted by a combination of endoglin-based DNA vaccine with IL-12 and the effect of this reversion on tumor blood vessels." (PMID 29320562, 2018). "Endoglin (ENG) is overexpressed on the surface of endothelial cells but also on some cancer cells (among others murine B16-F10 melanoma cells)." (PMID 29320562, 2018). "In conclusion, targeting endoglin for the treatment of melanoma seems to be a concept worthy of further exploration due to the increased therapeutic effect of the therapy based on simultaneous vascular targeting and its direct effect on tumor cells." (PMID 26712792, 2015). "The therapy significantly reduced the proliferation, survival and migration of melanoma cells, indicating the role of endoglin in regulating the different cellular properties of melanoma cells." (PMID 26712792, 2015). "Although significant changes in biological properties were observed in both melanoma variants, the effect was more pronounced in B16F1, probably due to a higher expression level of endoglin." (PMID 26712792, 2015). "The therapy significantly reduced the proliferation, survival and migration of melanoma cells, indicating the role of endoglin in regulating the different biological properties of melanoma cells." (PMID 26712792, 2015). "The results demonstrated that both melanoma cell lines and tumor models express high levels of endoglin." (PMID 26712792, 2015). "The results of our study clearly demonstrate the dual mechanism of action of the anti-endoglin therapy on blood vessels as well as on melanoma cells." (PMID 26712792, 2015). "The effectiveness of the therapy correlated with endoglin expression in melanoma cells; in vitro the effects were more pronounced in B16F1 cells, which express more endoglin than B16F10." (PMID 26712792, 2015). "The expression of endoglin in melanoma cells and tumors represented as mean delta Ct ± SEM (threshold cycle) values." (PMID 26712792, 2015). "Endoglin (CD105), a component of the TGFß1-R complex, was expressed on cultured and xenotransplant-derived melanoma cells in all patients (range: 32–63%), whereas in freshly isolated melanoma cells, CD105 was only expressed at very low or undetectable levels." (PMID 24489649, 2014). "To test whether endoglin regulates filopodia formation, we stably expressed endoglin-targeting shRNAs in B16F1 melanoma cells and confirmed that endoglin levels are reduced in both SEVs and cells." (PMID 41532547, 2026). "Endoglin expression has been previously detected in melanocytic lesions and in melanoma cell cultures, indicating a possible involvement of endoglin in the regulation of the biological properties of melanoma cells." (PMID 36150976, 2022). "Indeed, by promoting BMP signaling or by activating focal adhesion kinase (FAK) and PI3K pathways, ENG induces tumor plasticity in both Ewing sarcoma and melanoma." (PMID 33804796, 2021). "The data presented herein comprises optical images of melanoma cells and mice bearing xenografted murine melanomas at different time points after treatment with murine endoglin targeting liposomes (mEnd-IL) and also corresponding graphical data of the fluorescence intensities detected." (PMID 30225321, 2018). "Furthermore, microscopic images are shown demonstrating the localization of the liposomal fluorescence and melanin in the high endoglin -expressing murine melanoma cells." (PMID 30225321, 2018). "Endoglin expression has also been detected in several human melanocytic lesions and cultured melanoma cells, indicating the possible involvement of endoglin in the regulation of the biological properties of melanoma cells." (PMID 26712792, 2015).
melanoma (continued). "Therefore, to further elucidate the mechanisms behind this observation, the aim of our study was to explore the effect of endoglin silencing in melanoma on three different levels; cell cultures, 3D spheroids and tumors." (PMID 26712792, 2015). "Until now only a few studies have been conducted involving melanoma and endoglin." (PMID 26712792, 2015). "Therefore, we firstly examined the expression of endoglin in melanoma cells in vitro and subcutaneously induced melanoma tumors in C57Bl/6 mice in vivo." (PMID 26712792, 2015). "Finally, we tested the therapeutic potential of endoglin silencing in subcutaneously induced melanoma tumors in mice." (PMID 26712792, 2015). "These outcomes are consistent with our previous studies, where increased adhesion and reduced proliferation and migration were also observed in endothelial cells and the reduced number of metastases following endoglin silencing was demonstrated in the melanoma model." (PMID 26712792, 2015). "The results demonstrate that endoglin silencing with gene electrotransfer reduces the proliferation, survival and migration of melanoma cells and also has anti-tumor effectiveness, as the therapy resulted in a high percentage of tumor cures (23% and 58% on B16F1 and B16F10 tumors, respectively)." (PMID 26712792, 2015). "In conclusion, endoglin targeting for the treatment of melanoma seems to be a concept worthy of further exploration due to the increased therapeutic effect of the therapy based on the simultaneous vascular targeted effect as well as the direct effect on tumor cells." (PMID 26712792, 2015). "This could involve TGFβ as well as BMP signaling, as in Ewing sarcoma and melanoma cell lines endoglin was shown to lead also to higher BMP induced Smad1 phosphorylation." (PMID 23088614, 2012). "Thus, low CD105/ENDOGLIN expression is beneficial in melanoma patients." (PMID 40592236, 2025). "However, only a decrease in CD105/ENDOGLIN in melanoma patients translated in improved survival." (PMID 40592236, 2025). "Therefore, endoglin targeting in melanoma could benefit from an increased therapeutic effect based on simultaneously inhibiting angiogenesis and also the biological properties of melanoma cells (proliferation, migration, etc.)." (PMID 26712792, 2015). "Growth and angiogenic factors: angiopoietin-2, endoglin, fibroblast activation protein (FAP), melanoma inhibitory activity, and vascular endothelial growth factor-A (VEGF-A) were significantly (p < 0.0001) elevated in EC patients." (PMID 39511039, 2024). "We confirmed on cell cultures and 3D spheroids that silencing of endoglin with GET of pU6-antiCD105 plasmid alters the biological properties of both B16F1 and B16F10 melanoma." (PMID 26712792, 2015). "Indeed, recombinant human THSD7A fully rescued the filopodia defects of endoglin-KD for both HT1080 and B16F1 melanoma cells." (PMID 41532547, 2026). "We describe the clinical data of thin melanomas patients with and without metastases and the immunohistochemical expression of nestin, endoglin, and VEGF-C." (PMID 36150976, 2022). "Nestin (important in proliferation), endoglin (important in neovascularization), and VEGF-C (important in lymphangiogenesis) have already been described in cutaneous melanoma in general; but with little emphasis on thin melanomas." (PMID 36150976, 2022). "The therapy resulted in prolonged tumor growth delay, but no tumor cures were achieved, whereas in this study on endoglin expressing B16 melanoma tumors, a high percentage of tumor cures and longer growth delay of tumors were achieved." (PMID 26712792, 2015). "Likewise, the mouse melanoma cell line with high levels of stably transformed murine endoglin selectively took up mEnd-IL, but not FAP-IL, LipQ nor the free DY-676-COOH (B16F10-mEnd), which substantiates the target selectivity of the respective immunoliposomes." (PMID 28100205, 2017).